FAM13C (family with sequence similarity 13 member C)
Synonyms: FAM13C1
Tractability: No criterion of Open Targets' tractability assessment is met for any kind of drug.
Gene: Protein-coding gene on chromosome 10 (59,246,118 to 59,363,181, reverse strand). Ensembl gene ENSG00000148541.
Subcellular location (Human Protein Atlas): Cytosol; Nucleoplasm
Gene Ontology:
Molecular function: protein binding
Genetic constraint (gnomAD): Loss-of-function variants: 36 observed, 70.59 expected, observed/expected ratio (o/e) 0.51, 90% interval 0.39 to 0.67. The upper end of that interval is the gene's LOEUF score, 0.67, which puts it in group 2 of 6, group 1 being the genes least tolerant of losing a copy. Missense variants: 580 observed, 732.96 expected, observed/expected ratio (o/e) 0.79, 90% interval 0.74 to 0.85. Synonymous variants: 244 observed, 267.01 expected, observed/expected ratio (o/e) 0.91, 90% interval 0.82 to 1.02.
Homologues: Orthologues: macaque FAM13C (96% identical), rabbit FAM13C (89% identical), guinea pig FAM13C (88% identical), dog FAM13C (88% identical), chimpanzee FAM13C (85% identical), mouse Fam13c (84% identical), pig FAM13C (84% identical), rat Fam13c (81% identical), tropical clawed frog fam13c (55% identical), Drosophila melanogaster CG6424 (20% identical). Paralogues in human: FAM13A (36% identical), FAM13B (34% identical).
Diseases named in the same sentence as FAM13C in open-access papers:
FAM13C is named in the same sentence as 11 diseases in open-access papers, as found by Europe PMC text mining. Sharing a sentence is not in itself a finding about the gene and the disease. The quoted sentences say what the papers report.
prostate carcinoma (5 papers, 2017 to 2024). A carcinoma that arises from epithelial cells of the prostate gland. "At the same time, in humans FAM13C was shown to be associated with endometrial mixed adenocarcinoma as well as being used as a marker for prostate cancer or as a rectal adenocarcinoma survival predictor." (PMID 36292615, 2022). "To further extend our data on the relationship between FAM13C expression and different stages of benign and neoplastic prostate lesions, we analyzed a small “prostate cancer progression” TMA." (PMID 28415558, 2017). "Our immunohistochemical study on 9,633 prostate cancers strongly supports a relevant role of FAM13C in this disease." (PMID 28415558, 2017). "The comparison of FAM13C with established molecular features in prostate cancer demonstrated that increased FAM13C expression is strongly associated with the subset of tumors harboring the TMPRSS2:ERG gene fusion." (PMID 28415558, 2017). "In conclusion, the results of our study demonstrate that expression of FAM13C is an independent prognostic marker in prostate cancer." (PMID 28415558, 2017). "FAM13C overexpression was an independent prognostic marker in prostate cancer." (PMID 33680913, 2020). "In prostate cancer, FAM13C has gained interest because it is–despite of its unknown function-part of several RNA expression signatures for estimating prostate cancer aggressiveness, one of which has become commercially available." (PMID 28415558, 2017). "FAM13C, a gene with unknown function is included in several mRNA signatures for prostate cancer aggressiveness." (PMID 28415558, 2017). "In summary, the results of our study show that overexpression of FAM13C – a gene of largely unknown function-is a strong and independent prognostic feature in prostate cancer." (PMID 28415558, 2017). "To understand the impact of FAM13C on prognosis and its relationship to molecularly defined subsets, we analyzed FAM13C expression by immunohistochemistry on a tissue microarray containing 12,400 prostate cancer specimens." (PMID 28415558, 2017). "The recent availability of a FAM13C specific antibody facilitates large-scale in-situ analysis in order to clarify whether also FAM13C protein expression can serve as a prognostic marker in prostate cancer." (PMID 28415558, 2017). "The results of our study show that FAM13C overexpression is a strong predictor of poor clinical outcome in prostate cancer, and that its prognostic impact is independent of established pathological and clinical parameters." (PMID 28415558, 2017). "Although data on FAM13C expression have never been published in prostate cancer, the gene is a component of an expression signature, which is currently proposed for routine application as a commercially available prognostic test in prostate cancer." (PMID 28415558, 2017).
endometrial cancer (1 paper, 2023). Primary or metastatic malignant neoplasm involving the endometrium (mucous membrane that lines the endometrial cavity). "Our results showed that the expression levels of FAM13C, FAM72A and FAM11B were all significantly upregulated in endometrial cancer cells compared to normal endocervical cells." (PMID 37275958, 2023).
glioma (1 paper, 2017). A benign or malignant brain and spinal cord tumor that arises from glial cells (astrocytes, oligodendrocytes, ependymal cells). "FAM13C upregulation has been described in gliomas, liver cancers, and lymphomas as compared to their corresponding normal tissues." (PMID 28415558, 2017).
lymph node metastasis (1 paper, 2017). "This was also supported by our findings that strong FAM13C expression continuously increased from benign prostate lesions (BPH and PIN) to high Gleason grade cancers, lymph node metastasis and hormone refractory cancers." (PMID 28415558, 2017).
prostate tumors (1 paper, 2017). "Given that FAM13C staining was regularly found to be weak to moderate in normal prostate epithelium, these findings suggest that FAM13C becomes up regulated during tumor development and/or progression in a relevant fraction of prostate tumors." (PMID 28415558, 2017).
cancer (3 papers, 2017 to 2023). A tumor composed of atypical neoplastic, often pleomorphic cells that invade other tissues. "Interestingly, most of these genes are linked with cancer processes (Pld1, Fam13c, Svbp, TMem192, Zc3h7a, RTP4, Naa30, Zgrf1, Slc33a1, Dnmt3b, Map6, Plin4, Eps8L2, Alg12, Capg and Tdp2)." (PMID 37700325, 2023). "In cancer cells, positive FAM13C immunostaining was seen in 67.5% of our 9,633 interpretable tissues and was considered weak in 14.6%, moderate in 24.6% and strong in 28.3% of tumors." (PMID 28415558, 2017). "Data from other cancer types seem to suggest that FAM13C upregulation can occur in malignant tumors." (PMID 28415558, 2017). "In ERG negative cancers, FAM13C expression was also linked to deletions of 5q and 6q (p < 0.0001 each), although to a lesser extent as compared to PTEN deletions." (PMID 28415558, 2017). "That FAM13C expression was also found in cancer cells and also-typically at lower levels-in non-neoplastic tissues including luminal, basal and stroma cells further argues for a general metabolic function." (PMID 28415558, 2017). "FAM13C immunostaining was similarly linked to unfavorable tumor features in subsets of both ERG negative and ERG positive cancers." (PMID 28415558, 2017). "FAM13C (Family with sequence similarity 13, Member C), one of the FAM protein family, may be involved in intracellular signal transduction pathways relevant for cancer based on sequence analyses." (PMID 33680913, 2020).
tumor (3 papers, 2017 to 2024). "High levels of FAM13C staining were significantly linked to increased tumor cell proliferation (p < 0.0001)." (PMID 28415558, 2017). "ADIRF, tumor-associated genes CLU, FAM13C, as well as NGF, PRELP, RERG, PTGIS, GPC3 genes were among the top 20 overexpressed genes in EcE stromal cell population." (PMID 39169201, 2024). "Scenario 3 included FAM13C expression, preoperative PSA, clinical tumor stage (cT stage) and Gleason grade obtained on the prostatectomy specimen." (PMID 28415558, 2017). "We also evaluated the diagnostic potential of FAM13C, FAM110B, and FAM72A in distinguishing UCEC tissues from non-tumor tissues using ROC curves." (PMID 37275958, 2023). "Although the role of FAM family genes, such as FAM13C, FAM110B, and FAM72A, in UCEC remains unclear, their relevance to prognosis and the tumor immune microenvironment in UCEC patients warrants further investigation." (PMID 37275958, 2023).
FAM13C also shares sentences with these, for which no sentence is quoted: endometrial mixed adenocarcinoma (1 paper); liver cancer (1); lymphoma (1); rectal adenocarcinoma (1).